TTC22 (tetratricopeptide repeat domain 22)
Synonyms: FLJ20619
Tractability: No criterion of Open Targets' tractability assessment is met for any kind of drug.
Gene: Protein-coding gene on chromosome 1 (54,779,712 to 54,801,323, reverse strand). Ensembl gene ENSG00000006555.
Genetic constraint (gnomAD): Loss-of-function variants: 37 observed, 35.31 expected, observed/expected ratio (o/e) 1.05, 90% interval 0.81 to 1.38. The upper end of that interval is the gene's LOEUF score, 1.38, which puts it in group 5 of 6, group 1 being the genes least tolerant of losing a copy. Missense variants: 756 observed, 653.78 expected, observed/expected ratio (o/e) 1.16, 90% interval 1.09 to 1.23. Synonymous variants: 334 observed, 282.36 expected, observed/expected ratio (o/e) 1.18, 90% interval 1.08 to 1.29.
Homologues: Orthologues: chimpanzee TTC22 (99% identical), macaque TTC22 (97% identical), pig TTC22 (91% identical), rabbit TTC22 (90% identical), dog TTC22 (90% identical), rat Ttc22 (85% identical), mouse Ttc22 (84% identical), guinea pig TTC22 (60% identical), tropical clawed frog ttc22 (53% identical), zebrafish ttc22 (49% identical).
Diseases named in the same sentence as TTC22 in open-access papers:
TTC22 is named in the same sentence as 4 diseases in open-access papers, as found by Europe PMC text mining. Sharing a sentence is not in itself a finding about the gene and the disease. The quoted sentences say what the papers report.
colon cancer (2 papers, 2023 to 2025). "Our and others’ works indicate that miR663a inhibits the development and metastasis of colon cancer and that the miR663a target genes MALAT1 and TTC22 promote colon cancer metastasis." (PMID 37400477, 2023).
melanoma (1 paper, 2018). A malignant, usually aggressive tumor composed of atypical, neoplastic melanocytes. "Moreover, genes showing hypermethylation in melanoma such as KRTCAP3, AGAP2, ZNF490, and TTC22 were newly recognized in the present study." (PMID 30719424, 2018). "Furthermore, expression of AGAP2, ZNF490, and TTC22 was not decreased in melanoma (data not shown)." (PMID 30719424, 2018).
TTC22 also shares sentences with these, for which no sentence is quoted: cancer (1 paper); tumour (1).